MMP9 (matrix metallopeptidase 9)
Diseases named in the same sentence as MMP9 in open-access papers (continued):
Sharing a sentence is not in itself a finding about the gene and the disease.
head and neck squamous cell carcinoma (37 papers, 2007 to 2025). A squamous cell carcinoma that arises from any of the following anatomic sites: lip and oral cavity, nasal cavity, paranasal sinuses, pharynx, larynx, and salivary glands. "ETS1 is required for ZEB2-induced EMT phenotype, where it regulates ZEB2-mediated expression of Twist and MMP-9, and can function as a master regulator of TGF-β-associated EMT in the mesenchymal subtypes of head and neck squamous cell carcinoma (HNSCC)." (PMID 32824207, 2020). "For example, iron enhanced the expression levels of MMP-9, resulting in the development and progression of head and neck squamous cell carcinoma, as well as the activation of microglial cells." (PMID 33121166, 2020). "For instance, in head and neck squamous cell carcinoma (HNSCC), MMP9 and MMP2 exhibited a synergistic interaction that critically regulates tumor progression through coordinated modulation of cellular proliferation, migration, and invasive processes." (PMID 40666104, 2025). "Another study conducted an in vitro study examining the impact of α-mangostin on MMP-2 and MMP-9 expression in head and neck squamous cell carcinoma (HNSCC) cell lines (HN-22, HN-30, and HN-31)." (PMID 39595559, 2024). "In reviewing the literature on Head and Neck Squamous Cell Carcinoma (HNSCC), the overexpression of MMP-9 upregulated by Galectin-7 interacting with TCF3 might significantly promote lymph node metastasis." (PMID 37600570, 2023). "SNAI2 is an EMT-promoting TF that stimulates the expression of matrix metallopeptidase 9, thereby maintaining long-term EMT promotion in head and neck squamous cell carcinoma." (PMID 36567723, 2022). "Squamous cell carcinoma of the head and neck (SCCHN) patients with low interleukin 6 (IL-6) and high MMP9, or with high IL-6 and low MMP9, were found to have the poorest outcomes followed by patients with both high IL-6 and high MMP9." (PMID 32545247, 2020). "The over-expression of MMP9 and MMP2 has been observed in head and neck squamous cell carcinomas patients presenting with lymph node involvement." (PMID 31579438, 2019). "MMP7, MMP9, MMP11, MMP12 and MMP13 were all up-regulated in head and neck squamous cell carcinoma." (PMID 36941602, 2023). "Tumors with MMP-9 overexpression had significantly higher iNOS activity and cGMP levels compared with tumors that had absent or focal expression of MMP-9 in head and neck squamous cell carcinoma." (PMID 24325546, 2013).
intracerebral hemorrhage (37 papers, 2010 to 2026). A cerebrovascular disorder characterized by bleeding into one or both cerebral hemispheres including the basal ganglia and the cerebral cortex. "In a preclinical study, MMP-9 inhibition decreased the degree of brain edema, reduced the risk and gravity of intracerebral hemorrhage, and improved neurological outcome." (PMID 34685473, 2021). "Degradation of the vascular extracellular matrix by MMP‐9 is one important cause for vascular remodeling and angiogenesis, and may contribute to increase the risk of intracerebral hemorrhage." (PMID 31074588, 2019). "Other studies have found that JNK phosphorylates c-Jun to regulate MMP-9 transcriptional activity in the intracerebral hemorrhage (ICH) model." (PMID 39679379, 2024). "Our explanation for this result is that the destruction of the BBB is comediated by MMP-9 and collagenase in the acute phase (within the first 24 h) of collagenase-induced intracerebral hemorrhage in rats." (PMID 36865920, 2023). "Significantly increased plasma MMP-9 concentration (191.4 ng/ml) was detected in patients who later suffered from the parenchymal intracerebral hemorrhage in comparison to the control group (68.05 ng/ml)." (PMID 31701356, 2020). "A predictive value of increased level of MMP-9, regarding threatening intracerebral hemorrhage, was raised in patients treated with thrombolytic therapy." (PMID 31701356, 2020). "In a mouse model of intracerebral hemorrhage, increased expression of Tlr2 was observed, resulting in a proinflammatory gene profile with activation of Mmp9." (PMID 31083655, 2019). "The effects of performing a minimally invasive procedure at different stages after intracerebral hemorrhage on perihematomal MMP-9 expression and blood–brain barrier (BBB) permeability were evaluated." (PMID 24739149, 2014). "Wang and Tsirka showed that systemically intraperitoneal administration of broad-spectrum MMPs’ inhibitor (GM6001) reduces the intracerebral hemorrhage-induced gelatinolytic activity by reduction of pro- and active MMP-9 (and pro-MMP-2) proteins levels." (PMID 24918931, 2014). "This aligns with preclinical evidence showing atorvastatin reduces matrix metalloproteinase‐9 (MMP‐9) activity, preserving BBB integrity after intracerebral hemorrhage." (PMID 40717327, 2025). "Previous histologic studies in occipital lobe showed an altered ratio of MMP9 and TIMP3 in leptomeningeal vessels of CAA cases with intracerebral hemorrhage." (PMID 39039355, 2024). "In TLR2−/− mice, activation of the matrix metalloproteinase-9 (MMP9) in astrocytes was lower than in wild type (WT) mice, and this reduction resulted in attenuated damage to the BBB in TLR2−/− mice with intracerebral hemorrhage." (PMID 31998072, 2019). "However, data from experiments using MMP-9 KO and MMP-3 KO mice suggest that MMP-3 contributes to delayed tPA-induced intracerebral hemorrhage more than MMP-9 does." (PMID 39000490, 2024).
ulcerative colitis (37 papers, 2012 to 2025). An inflammatory bowel disease involving the mucosal surface of the large intestine and rectum. "Matrix metalloproteinase-9 [MMP9] is implicated in the pathogenesis of ulcerative colitis [UC] via disruption of intestinal barrier integrity and function." (PMID 29767728, 2018). "Dysregulated MMP9 expression and activity are associated with several inflammatory disorders, including ulcerative colitis (UC)." (PMID 25961845, 2015). "An MMP-9-specific Mab, GS-5745, is undergoing a randomized phase 1 clinical trial for the treatment of ulcerative colitis after in vivo animal studies." (PMID 40565017, 2025). "An increased concentration of MMP-9 is observed in the plasma from patients with active ulcerative colitis and active Crohn’s disease." (PMID 39327633, 2024). "In recent studies, it was demonstrated that deflamin, a protein component extracted from Lupinus albus, markedly inhibits the catalytic activity of MMP-9 in experimental models of colon adenocarcinoma and ulcerative colitis." (PMID 38791100, 2024). "The experiment confirmed that MMP-9 levels were significantly higher in cases of active intestinal inflammation and ulcerative colitis." (PMID 38203373, 2023). "The study observed that serum MMP-9 concentrations were higher in patients with active ulcerative colitis compared to patients with inactive disease." (PMID 38203373, 2023). "Shamseya and coworkers reported also that in both ulcerative colitis and CD patients, there were lower serum levels of MMP-9 in patients receiving biologics compared to those receiving conventional treatments." (PMID 35620197, 2022). "In preclinical investigations, inhibition of MMP9 reduced disease severity in a mouse model of ulcerative colitis, and decreased tumor growth and metastasis in a surgical orthotopic xenograft model of colorectal carcinoma." (PMID 34577904, 2021). "Metalloproteinases such as MMP-9 induce inflammatory damage on tissues by cleaving extracellular matrix proteins, and that by itself can aggravate ulcerative colitis." (PMID 33519451, 2020). "In preclinical investigations, MMP-9 inhibition reduced the disease severity in a mouse model of ulcerative colitis and it decreased tumor growth and metastases incidence in a surgical orthotopic xenograft model of colorectal carcinoma." (PMID 31216704, 2019). "The expression and activities of MMP2 and MMP9 were increased in different models of experimental colitis, moreover, MMPs were overexpressed in the inflamed tissue of patients with ulcerative colitis." (PMID 28797051, 2017). "Levels of phosphorylated signal transducer and activator of transcription 3(STAT3) regulated the MMP-9 gene in pediatric patients with ulcerative colitis." (PMID 24476461, 2014). "Additionally, elevated concentrations of MMP-2 and MMP-9 in the plasma positively correlate with high intestinal permeability in ulcerative colitis patients." (PMID 39327633, 2024). "It was shown that MMP-9 is one of the key enzymes involved in the degradation of intestinal tissue during an inflammatory disease of gastrointestinal tract, for example, Crohn's disease (CD) and ulcerative colitis (UC)." (PMID 35340213, 2022). "In ulcerative colitis, excess MMP-9 activity leads to destruction of the intestinal barrier." (PMID 33995942, 2021). "In an immunohistochemical study we demonstrated that the mucosal up-regulation of MMP-9 correlated with the severity of inflammation in ulcerative colitis (UC), suggesting that the increased MMP-9 expression could contribute to the severity of mucosal damage in active UC." (PMID 23202950, 2012). "Ulcerative colitis is a chronic inflammatory bowel disease in which the level of MMP3 and MMP9 is increased in human patients." (PMID 36552443, 2022). "The aim of our study was to evaluate the expression of MMP-2, MMP-7, MMP-9, TIMP-1, and TIMP-2 in ulcerative colitis and Crohn's disease." (PMID 27034654, 2016).
ulcerative colitis (continued). "MMP-9 and MMP-14-specific Mabs have been evaluated in cancers such as breast tumors and gastric and gastroesophageal junction adenocarcinoma and in autoimmune disease like ulcerative colitis." (PMID 40565017, 2025). "Ulcerative colitis in rats increased the expression of TNF-α, MMP9 and IL-13." (PMID 38321559, 2024). "Matrix Metaloproteinase-9 (MMP-9) and Tissue Inhibitor of Metaloproteinase-1 (TIMP-1), enzymes involved in tissue remodelling, have been previously reported to be overexpressed in the colonic mucosa of patients with Ulcerative colitis (UC)." (PMID 35566780, 2022). "Here, we show that selective inhibition of MMP9 did not induce musculoskeletal syndrome (a characteristic toxicity of pan-MMP inhibitors) in a rat model, but did reduce disease severity in a dextran sodium sulfate-induced mouse model of ulcerative colitis." (PMID 25961845, 2015).
kidney damage (36 papers, 2007 to 2025). "Both MMP-2 and MMP-9 are implicated in vascular damage processes and are associated with kidney damage, making their elevation particularly unfavorable in diabetic patients." (PMID 39685536, 2024). "MMP-9 activation is closely linked to albuminuria/proteinuria in animal models of proteinuric kidney diseases and in human nephropathies." (PMID 28805677, 2017). "Polymorphisms in the CCR5 and MMP9 have been also reported to be associated with the increased risk of nephropathy." (PMID 19357773, 2009). "Frequency of CCL2 II, IL8 -251AA, CCR5 59029AA and MMP9 279Gln/Gln genotypes were significantly higher in DN than in DM group (p<0.05) and associated with an increased risk of nephropathy in both North and South Indian cohorts." (PMID 19357773, 2009). "The co-occurrence of risk associated genotypes (II, -2518GG (CCL2), DD (CCR5) and 279Gln/Gln (MMP9) conferred a tenfold increased risk of nephropathy among type 2 diabetics (p<0.0002)." (PMID 19357773, 2009). "The cellular sources of MMP-9 are associated with different stages of nephropathy." (PMID 38260142, 2023). "MMP9 has previously been shown to be produced by podocytes 16, 33 and altered in a number of glomerular diseases, including lupus nephritis with active, fibrocellular crescents 40, DN 33, 41; viral‐associated glomerulonephritis 42, membranous 43 and hypertensive 44 nephropathy." (PMID 30125361, 2018). "The ALS group exhibited the highest mean levels of active MMP-9 of all of the groups, which was significantly higher than that of Alzheimer’s (p = 0.023), and HC groups (p < 0.0001), and higher than the nephropathy (p = 0.714)." (PMID 41009467, 2025). "Novel kidney injury biomarkers (IL-6, IL-8, TNF-α, NGAL, KIM-1, MMP-9, and IL-18) were used in this investigation to assess kidney damage more accurately." (PMID 38420620, 2024). "In a diabetic rat model, serum and urine concentrations of MMP9 increased in the very early stage of nephropathy, with a higher MMP9 expression level in the proximal tubular epithelial cells." (PMID 37445827, 2023). "Although there is a controversy about the MMP-9 and Timp-1 relationship with kidney damage and CKD, some studies showed a contribution to fibrosis by the higher expression of MMP-9 and lower expression of Timp-1, and others revealed contrary observations." (PMID 35628203, 2022). "MMP-9 is directly connected with the degree of proteinuria and is recognized as a marker of kidney damage." (PMID 34402375, 2021). "Among them, MMP-9 levels were directly correlated with the degree of proteinuria, the main sign of kidney damage, which accelerates the progression of CKD toward ESKD and significantly increases the CV risk as well." (PMID 33573220, 2021). "MMP-9 is observed upregulated in various nephropathies because of its promotive effect on the development of fibrin-induced glomerular lesions." (PMID 32908562, 2020). "For example, high levels of serum MMP-9 and a high MMP-9-to-TIMP ratio have been related to retinopathy, and high levels of plasma MMP-10 have been associated with nephropathy and proliferative retinopathy." (PMID 25848912, 2015). "MMP-9 knockout in diabetic mice prominently decreased the nephropathy changes." (PMID 36577761, 2022). "It has, thus, been postulated that the increase in NGAL may prolong the action of MMP-9 as a trigger of kidney damage." (PMID 31963569, 2020). "In the DM population, the expression of MMP-2 and MMP-9 is altered, which contributes to microangiopathic and macroangiopathic complications, such as nephropathy, with MMP-2 being a good index of microangiopathy severity and MMP-9 being a good marker of macroangiopathy." (PMID 33419373, 2020). "Local secretion of MMP-9 may play an important role in nephropathy progression by facilitating the degradation of the tubular basement membrane, resulting in an inflammatory and fibrotic response in the interstitium of diabetic kidneys." (PMID 28805677, 2017).
kidney damage (continued). "The results indicate that plasma MMP-2 may play a role in the pathogenesis of equine colic and urinary MMP-9 in equine kidney damage." (PMID 17244354, 2007). "MMP-9, a matrix metalloproteinase involved in extracellular matrix remodeling, is closely associated with fibrosis, and its elevated levels, along with the concurrent rise in CLU, suggest that fibrotic changes contribute significantly to kidney damage at this stage." (PMID 40428765, 2025). "Key biomarkers, including matrix metalloproteinase 9 (MMP-9) and intercellular adhesion molecule (ICAM-1), are involved in driving kidney damage through inflammatory processes and fibrosis." (PMID 40422591, 2025). "Nebivolol attenuated kidney damage, reducing the expression and level of MMP-2 and MMP-9, as indicated in a rat model of ischemia-reperfusion injury." (PMID 35629096, 2022). "For example, the most frequently studied MMPs in HF and kidney damage are MMP-2 and MMP-9, out of which MMP-9 is believed to have a profibrotic effect whereas MMP-2 has antifibrotic effects." (PMID 34359993, 2021). "This study suggests that plasma levels of TIMP-1, MMP-9 and NGAL may serve as useful biomarkers in unravelling subclinical neuropathy and nephropathy in type 1 diabetes." (PMID 33775157, 2021). "Indeed, increased levels of MMP-2 and MMP-9 and ADAM-17 promote inflammation, atrophy and fibrosis of renal tissue, thus accelerating kidney damage in CKD patients." (PMID 33573220, 2021).
viral infection (36 papers, 2009 to 2025). "High MMP9 expression alters the blood–brain barrier permeability, increasing the possibility of viral infections and susceptibility to inflammatory factors and inflammatory cell infiltration." (PMID 36998608, 2023). "Our results showed that macrophage migration in MO zebrafish was increased, which is concordant with the high expression of mmp9. mmp9 has been found to be associated with numerous pathological processes, including cancer, viral infection, and blood lipoprotein levels." (PMID 32321550, 2020). "Overproduction of MMP9 following viral infection is associated with vascular leakage." (PMID 26284919, 2015). "Hence, the current investigation has highlighted new knowledge of sivelestat as potent MMP-2, MMP-9, chikungunya nsP2 protease, and influenza neuraminidase inhibition activities, which help in the management of inflammation and viral infection-associated diseases." (PMID 38659558, 2024). "This leads to the hypothesis that prenatal environmental risk factors for ADHD, such as viral infections, asphyxia, neurotoxins, alcohol or nicotine can affect the expression of MMP-9, and consequently the long-term alteration in blood–brain barrier permeability to small-molecular-weight markers." (PMID 24633733, 2015). "Viral infections of the CNS are associated with the macrophage-induced production of MMP-2, MMP-7, and MMP-9, while LPS can directly induce MMP-9 expression in rat astrocytes, in relevance to neuroinflammatory states." (PMID 40332093, 2025). "Specifically, as the duration of viral infection increased, the secretion of MMP-9 by astrocytes increased." (PMID 40176142, 2025). "Expression of these genes is associated with movement (MMP9, SPP1, ALCAM, and others), viral infection (APOC1, LGALS3, CD63, and others), and recruitment of phagocytes (APOE, CHI3L1, LGALS3, and others)." (PMID 32723919, 2020). "The viral infection rate in EGFP-CA16 + MMP9 monkeys was higher than that in EGFP-CA16 monkeys and further higher than that in EGFP-CA16 + TIMP-1 monkeys." (PMID 30228270, 2018). "In the brain, activity of MMP2, MMP3, and MMP9 is induced under pathological conditions, including viral infection." (PMID 27303733, 2016). "Up-regulation of MMP-9 by viral infection has been shown to trigger tissue injury in various organs." (PMID 22251375, 2012). "Previous studies have indicated that several signaling cascades are involved in MMP-9 expression by virus infection." (PMID 22251375, 2012). "On the other hand, MMP-2 and MMP-9 play essential roles in placental ECM turnover during normal pregnancy; however, their dysregulation has been implicated in pathological processes such as preterm labor and vertical transmission of viral infections." (PMID 41465558, 2025). "Virus infections have been shown to modulate MMP-9 expression." (PMID 37447286, 2023). "MMP-9, a type of matrix metalloprotease, has been found to be increased during viral infections." (PMID 32823491, 2020). "MMP9 can be upregulated by multiple viral infections, triggering a series of downstream effects." (PMID 32302362, 2020). "Nevertheless, we show for the first time that MMP9 may contribute to pathogenesis by mediating excessive neutrophil migration into the respiratory tract in response to viral infection." (PMID 22496659, 2012). "However, upon injury such as mechanical trauma, thermal burn, and viral infection, MMP-9 is promptly elevated, indicating its role in wound healing by activating the stromal cells, releasing growth factors, and initiating cell migration." (PMID 19298660, 2009). "Moreover, findings support a central role of MMP-9 in T-cell migration and in disruption of vascular basement membranes, and this protein has recently been shown to act directly in the blood-brain barrier after virus infection." (PMID 20831786, 2010).